MTOR (mechanistic target of rapamycin kinase)
Diseases named in the same sentence as MTOR in open-access papers (continued):
Sharing a sentence is not in itself a finding about the gene and the disease.
lupus nephritis (continued). "We used our own data (presented here) and previously published data on the efficacy of mTOR inhibitors in two mouse models of lupus nephritis to infer that perturbations of the mTOR pathway are critical to the development of lupus nephritis in both these models." (PMID 18980674, 2008). "Therefore, mTOR inhibitors may have a role in the clinical management of lupus nephritis patients, especially in those who cannot tolerate standard-of-care treatments." (PMID 35571122, 2022). "In NZB/W F1 lupus-nephritis mice, MMF plus rapamycin improved nephritis, suppressed mTOR/ERK signaling, and reduced TGF-β1, MCP-1, α-SMA, fibronectin and collagen." (PMID 40650314, 2025). "Intraperitoneal delivery of miR-183 mimics to MRL/lpr mice attenuated murine lupus nephritis with reduced anti-dsDNA antibodies, BUN through targeting mTOR." (PMID 35873462, 2022). "Networks were built in an effort to understand the broad ranging beneficial effects of the mTOR pathway inhibitor, sirolimus, in NZB/W lupus nephritis." (PMID 18980674, 2008). "Treatment with sirolimus, a mammalian target of rapamycin (mTOR) inhibitor, has been shown to be efficacious in the MRL/lpr and NZB × NZW F1 mouse models of lupus nephritis, indicating a critical role for the mTOR pathway in both models." (PMID 18980674, 2008). "Also, sirolimus (mTOR inhibitor) serves as a treatment for lupus nephritis when the standard therapy is not tolerated." (PMID 38500390, 2024). "Data from our in vitro studies demonstrated that induction of mTOR and ERK phosphorylation, α-smooth muscle actin, and mediators of fibrosis by IL-6 was comparable to that observed with TGF-β1, and it is plausible to suggest that IL-6 may contribute to kidney fibrosis in lupus nephritis." (PMID 35571122, 2022).
non-Hodgkin lymphoma (27 papers, 2010 to 2025). Distinct from Hodgkin lymphoma both morphologically and biologically, non-Hodgkin lymphoma (NHL) is characterized by the absence of Reed-Sternberg cells, can occur at any age, and usually presents as a localized or generalized lymphadenopathy associated with fever and weight loss. "One previous study demonstrated synergism of KPT-330, an mTOR inhibitor (everolimus), and dexamethasone in non-Hodgkin's lymphoma." (PMID 34628286, 2021). "The overactivation of the PI3K/mTOR signaling pathway in non-Hodgkin lymphoma made the corresponding inhibitor BEZ235 a very promising treatment." (PMID 33916177, 2021). "The majority of studies of the mTOR signal pathway in non-Hodgkin lymphomas have been performed on cell lines." (PMID 28192480, 2017). "Preclinical evaluation of dual mTOR-HDAC inhibition in non-Hodgkin lymphoma cells showed that the mechanisms of effectiveness of both drugs were largely retained." (PMID 29299126, 2017). "A phase I clinical trial combining the HDAC inhibitor panobinostat with the mTOR inhibitor everolimus is currently enrolling patients with non-Hodgkin's lymphoma (NHL) and HL." (PMID 25006506, 2014). "Recently, the mammalian target of rapamycin (mTOR) inhibitor everolimus was shown to act synergistically with gemcitabine or paclitaxel for treatment against non-Hodgkin lymphoma (NHL) cell lines." (PMID 25013742, 2013). "mTOR activity and the elements of mTOR complexes were investigated by immunohistochemistry on tissue microarrays representing different human non-Hodgkin-lymphomas (81 cases) and Hodgkin-lymphomas (87 cases)." (PMID 23693095, 2013). "Its expression is activated in 93% of HL cases and the mTOR inhibitor Everolimus is considered an antiproliferative agent as well as targeted treatment for refractory/relapsed HL, while a combination of Akt and mTOR inhibitors can be effectively treated in non-Hodgkin lymphomas." (PMID 40896706, 2025). "Like mTOR inhibitors, the dual PI3K-mTOR inhibitors have shown promising anti-tumour activity in various preclinical models and tested in clinical trials of advanced solid tumours and non-Hodgkin lymphoma." (PMID 40805230, 2025). "Also, mTOR shares some signaling pathways with RGS1 as the PI3K/Akt cell cycling pathway, which contributes to the initiation and maintenance of cancer as in Non-Hodgkin lymphomas." (PMID 37437037, 2023). "Based upon preclinical data showing synergy with combined mTOR and HDAC targeting, a Phase 1 trial in both relapsed non-Hodgkin lymphoma (NHL) and HL of everolimus and the HDAC inhibitor panobinostat was performed and resulted in a similar 43% response rate in patients with HL." (PMID 24904824, 2014).
Salmonella Infections (27 papers, 2015 to 2025). Infections with bacteria of the genus SALMONELLA. "In the positive ion mode, KEGG pathway analysis demonstrated statistically significant enrichment of the mTOR signaling pathway and Salmonella infection, along with elevated pathway activity in Chagas disease (American trypanosomiasis)." (PMID 40806239, 2025). "KEGG pathway analysis indicated that the target RNAs were enriched in pathways, including Herpes simplex virus 1 infection, Endocytosis, Salmonella infection, Ubiquitin mediated proteolysis, and mTOR signaling pathway." (PMID 39224379, 2024). "These pathways include Ras signaling pathways (oas04014), endocytosis (oas04144), Salmonella infection (oas05132), mTOR signaling (oas04150), cell adhesion molecules (oas04514), tight junction (oas04530), and leukocyte trans endothelial migration (oas04670)." (PMID 39062990, 2024). "AMPK and mTOR pathways are an important link between the extracellular environment and intracellular metabolism during Salmonella infection to young chickens." (PMID 35847587, 2022). "mTOR is a sensor and regulator of immunometabolic changes during Salmonella infection in the chicken." (PMID 33225883, 2020). "Our results are in line with activation of mTOR pathway in the course of Salmonella infection of macrophages as reflected by increased phosphorylation of the downstream target of mTOR, 4E-BP1." (PMID 31832425, 2019). "In summary, this study demonstrated BCA induced AMPK/ULK1/mTOR-mediated autophagy and METs, which enhanced the defense against Salmonella infection in vitro and in vivo." (PMID 30271755, 2018). "mTOR signaling was known to be altered after Salmonella infection and mTOR is a phosphoproteomic hit having significant effect at 10 min in our data." (PMID 26257716, 2015). "In several studies, Salmonella infection was shown to down-regulate mTOR pathway to induce apoptosis." (PMID 26257716, 2015). "Meanwhile, the expression of phospho-AKT/phospho-mTOR was reduced after the Salmonella infection." (PMID 29857512, 2018). "In addition, Western blot analysis showed that the expression levels of phospho-AKT (P-AKT), phospho-mTOR (P-mTOR), and phospho-p70s6K(P-p70s6K) in tumor cells were decreased after Salmonella infection." (PMID 27175584, 2016). "Several pathways such as SNARE binding, mTOR signaling, immune response, cytoskeleton organization, and apoptosis, were found to be effected, many of which were previously found to be altered in the host cell after Salmonella infection." (PMID 26257716, 2015). "A Salmonella infection could influence the AKT/mTOR signaling pathways in cells." (PMID 29857512, 2018). "A recent report showed that biochanin A improved defense against Salmonella infection both in vivo and in vitro by activating AMPK/ULK1/mTOR-mediated autophagy and macrophage extracellular traps (METs)." (PMID 35448466, 2022). "One of the downstream signaling of EGFR involves mTOR and HIF-1α axis, which was also found to be significantly affected by Salmonella infection in THP-1 cells." (PMID 33868285, 2021). "In a temporal gene expression analysis, where the Bayesian network analysis is used, the immune response, Wnt, PI3K, mTOR, TGF-β, and many other signaling pathways were found to be altered during the Salmonella infection." (PMID 26257716, 2015). "KEGG analysis of the differential genes also revealed functional diversity, involving Cyanoamino acid metabolism, Salmonella infection, ABC transporters, Choline metabolism in cancer, Nonribosomal peptide structures, Regulation of actin cytoskeleton, mTOR signaling pathway, and other." (PMID 37125200, 2023).
Thrombocytopenia (27 papers, 2009 to 2025). A reduction in the number of circulating thrombocytes. "Sirolimus (rapamycin), an mTOR inhibitor, has demonstrated clinical efficacy in treating SS-associated thrombocytopenia." (PMID 41255601, 2025). "We conjectured that the molecular mechanism of TMEA action in thrombocytopenia is likely related to the TMEA interaction with the hub protein mTOR." (PMID 34485295, 2021). "Activation of mTOR and efficacy of therapeutic blockade was previously demonstrated in thrombocytopenia secondary to SLE." (PMID 32296709, 2020). "In two preliminary reports of studies combining sorafenib with mTOR inhibitor temsirolimus, significant toxicity was described including mucocutaneous toxicity, serum transaminase elevations, hypertrygliceridemia and thrombocytopenia." (PMID 21045832, 2010). "The mTOR inhibitor sirolimus, which preferentially inhibits mTORC1, has led to sustained remission in a small cohort of anti‐IL‐6‐refractory iMCD patients with thrombocytopenia, anasarca, fever, renal dysfunction and organomegaly (iMCD‐TAFRO)." (PMID 35488725, 2022). "The PI3K/mTOR inhibitor BEZ-235 could also efficiently be applied in combination with AZD-5991, offering an alternative to avoid thrombocytopenia which is associated with the use of BCLXL inhibitors." (PMID 35058488, 2022). "Furthermore, we observed the remarkable activation of MAPK and mTOR occurred in platelet lysate from patients with thrombocytopenia." (PMID 35450072, 2022). "Second, network pharmacology predicted that the molecular mechanism of AECRs in the treatment of thrombocytopenia was closely related to the PI3K/AKT, JAK/STAT, RAS, MAPK, and mTOR pathways." (PMID 36430539, 2022). "mTOR inhibitors was not discontinued in any of the patients, although six patients (7.1%) developed thrombocytopenia after mTOR inhibitor use." (PMID 34326770, 2021). "Given that BCL-XL inhibitors including navitoclax cause thrombocytopenia, a combination of navitoclax with AZD8055 (or another mTOR inhibitor) may not be clinically feasible." (PMID 36588105, 2023).
urothelial carcinoma (27 papers, 2011 to 2025). A malignant neoplasm derived from the transitional epithelium of the urinary tract (urinary bladder, ureter, urethra, or renal pelvis). "Akt–mTOR pathway activation has recently been shown to be associated with cisplatin-resistance in urothelial carcinoma cells, and suppression of it restored sensitivity to cisplatin in vitro and in vivo." (PMID 36232303, 2022). "It is estimated that approximately 40 % of urothelial carcinomas have PI3K/Akt/mTOR pathway activating mutations." (PMID 26931119, 2016). "PTEN, a tumor suppressor gene that negatively regulates activation of the PI3K/Akt/mTOR pathway, is deficient in over 50 percent of urothelial carcinomas due to loss of heterozygosity (LOH)." (PMID 25909217, 2015). "Some previous studies have revealed that the PI3K/AKT/mTOR was dysregulated in over 40% of patients with urothelial carcinoma." (PMID 39757744, 2025). "An integrated analysis of 131 urothelial carcinomas has identified the Akt/mTOR pathway as a potential therapeutic target in 42% of these tumors." (PMID 35057550, 2022). "In this review, we highlight the functional significance of mTOR signaling in urothelial carcinoma and its potential impact on future therapy implications." (PMID 35326708, 2022). "High levels of mTOR activity are found in approximately 70% of urothelial carcinomas, implicating a key role of this pathway in these cancers." (PMID 36230603, 2022). "The PI3K pathway is upstream of the protein kinase B (Akt) and mammalian target of rapamycin (mTOR) pathways, with PIK3CA mutations and subsequent upregulation of the PI3K pathway common in urothelial carcinoma." (PMID 36358849, 2022). "It has already been mentioned that Akt/mTOR signaling pathway is activated in bladder tumor sample, emphasizing the importance of this pathway in the progression of urothelial carcinoma and making this pathway become a potential target." (PMID 28746469, 2017). "Activation of the phosphoinositide-3-kinase (PI3K)-Akt-mTOR (mammalian target of rapamycin) pathway occurs in urothelial carcinomas, particularly in muscle-invasive tumors." (PMID 25909217, 2015). "Accordingly, mTOR is important in urothelial carcinoma and identification of the mechanism of mTOR regulation in urothelial carcinoma is necessary." (PMID 25596749, 2015). "Inhibitors of the mTOR have demonstrated anti-tumor activity alone and in combination with chemotherapy, as mTOR inhibition enhances chemosensitivity of urothelial carcinoma cells." (PMID 25909217, 2015). "PI3-kinase and AKT cause an upregulation of p21 by suppressing GSK-3β activity and activating mTOR in both cultured human urothelial carcinoma cells and mouse urothelial cells in vivo." (PMID 21864408, 2011). "Genetic alterations in the PI3K/Akt/mTOR pathway are common in urothelial carcinoma." (PMID 35406567, 2022). "mTOR pathway abnormalities have been found in approximately 70% of urothelial carcinomas (UCs)." (PMID 35326708, 2022). "Another study found that CCL18 could promote the invasiveness and metastasis of urothelial carcinoma through activation of the phosphatidylinositol-3-kinase (PI3K)/AKT/mammalian target of rapamycin (mTOR) signaling pathway." (PMID 36131933, 2022). "Therefore, targeting the Akt-mTOR pathway is an attractive strategy to treat advanced urothelial carcinoma, and several mTOR inhibitors are clinically applied." (PMID 32512849, 2020). "The regulation of S6K by 3-phosphoinositide dependent protein kinase-1 (PDK-1) may explain the difference in inhibition of p-mTOR and p-S6 status as demonstrated after rapamycin treatment in urothelial carcinoma." (PMID 29100343, 2017). "Aberrant activation and mutation status of proteins in the phosphatidylinositol-3-kinase (PI3K)/Akt/mammalian target of rapamycin (mTOR) and the mitogen activated protein kinase (MAPK) signaling pathways have been linked to tumorigenesis in various tumors including urothelial carcinoma (UC)." (PMID 22110663, 2011).
urothelial carcinoma (continued). "Furthermore, the SLC14A1 gene is also considered a novel tumor suppressor for urothelial carcinoma, and in PCa, the downregulation of its expression promotes tumor progression by activating the CDK1/CCNB1 and mTOR pathways and is closely associated with biochemical recurrence (BCR) of PCa." (PMID 40260298, 2025). "Recently, we demonstrate that rapamycin, the mammalian target of rapamycin (mTOR) inhibitor, exhibits potent anti-tumor properties against BBN-induced urothelial carcinoma." (PMID 25596749, 2015). "There may still be a possibility of finding a tolerable combination of PI3k/Akt/mTOR inhibitor and MAPK pathway inhibitor in urothelial carcinoma." (PMID 35406567, 2022).
focal epilepsy (26 papers, 2014 to 2025). A seizure caused by a localized disorder. "For instance, DEPDC5, a component of the GATOR1 complex and a negative regulator of mTOR, has been identified as a gene associated with focal epilepsy in humans." (PMID 34309811, 2021). "The mTOR genes including DEPDC5, TSC1 and TSC2 have been associated with focal epilepsy, as was the case in our study in which the mTOR genes had the highest yield (13/32), although the yield was relatively low in some previous studies." (PMID 31875159, 2019). "Recent studies have indicated that somatic variants confined to the brain may contribute to the yet largely undescribed genetics of focal epilepsies, particularly in genes associated with the mTOR pathway." (PMID 37834053, 2023). "Our current findings suggest that mTOR dysregulation may well be more generally implicated in pathogenesis of varied acquired lesions in focal epilepsies, particularly in the presence of dysmorphic cytopathology; the causes of this deserve further investigation." (PMID 25005575, 2014). "Recent studies have linked mutations in several genes involved in the mTOR signaling pathway - such as TSC1, TSC2, MTOR, DEPDC5, NPRL2, and NPRL3 - to the development of focal epilepsies in affected individuals." (PMID 40546503, 2025). "For instance, DEPDC5 mutations have been associated with various focal epilepsies, including TLE, through dysregulation of the mTOR pathway, which controls neuronal growth and excitability." (PMID 41244607, 2025). "The other interesting gene identified was NPRL3 (case 10), which involves the mTOR pathway and an increasingly important gene identified in the drug-resistant focal epilepsies." (PMID 35888005, 2022). "The amino acid-sensing arm of the mTOR cascade has garnered recent attention due to its role in a number of genetic focal epilepsies and DEEs." (PMID 34632383, 2021). "In focal epilepsy due to genetic etiology, growing attention has been directed to genes involved in the mTOR signaling pathway, which triggers many biological processes including cell growth, proliferation, and apoptosis, primarily through regulation of the cell cycle." (PMID 40971258, 2025). "We have documented 10 patients with focal epilepsy carrying pathogenetic variants (8/10) or variants of uncertain significance (2/10) in the mTORC1 pathway genes (DEPDC5, NPRL3, and MTOR) who developed central apnea in 100% of their seizures, for a total of 31 seizures with respiratory alterations." (PMID 40971258, 2025). "The sheer nature of epileptic seizures, which are characterized by a large-scale hypersynchronous activity of neuron populations, make the use electroencephalography (EEG) particularly relevant in the study of focal epilepsies, such as mTOR-related epileptic syndromes." (PMID 36639812, 2023). "Pathogenic variants in any number of genes involved in the mTOR pathway have been linked to focal epilepsy, both with and without brain malformations." (PMID 37834053, 2023). "Defects in the mTOR pathway play an important role in focal epilepsy during brain development." (PMID 34376795, 2022). "The detection of an increasing number of patients with GATOR1 complex mutations and further investigations into the mechanisms of mTOR pathway signaling and GATOR1 pathogenesis in focal epilepsies present exciting potentials for future therapeutic interventions." (PMID 34868250, 2021). "Our results reveal the mechanisms of mTOR pathway signaling and GATOR1 pathogenesis in focal epilepsies." (PMID 34868250, 2021). "Clock genes such as CLOCK may play an essential role in the generation of focal epilepsy, such as FCD type II, which is paradigmatic mTOR-opathy." (PMID 32457690, 2020). "Our study possibly reveals causal genetic variants in 13.2% of non-familial patients with predominantly focal epilepsy in which mTOR genes and ion channel-related genes are most commonly associated." (PMID 31875159, 2019).
focal epilepsy (continued). "Notably, we did not see an overrepresentation of PI3K/Akt/mTOR genes (eTable 3 in Supplement 1) in the MTLE cohort, further supporting the notion that focal epilepsies in the temporal lobe share a genetic etiology distinct from focal extratemporal epilepsies." (PMID 37126322, 2023). "We also examined the burden in the mTOR pathway (KEGG), hypothesizing that it could have potential relevance to focal epilepsies, but did not detect a substantial enrichment." (PMID 34571366, 2021).